RAPGEF4 (Rap guanine nucleotide exchange factor 4)
Description:
Guanine nucleotide exchange factor (GEF) for RAP1A, RAP1B and RAP2A small GTPases that is activated by binding cAMP. Does not seem to activate RAB3A. Involved in cAMP-dependent, PKA-independent exocytosis through interaction with RIMS2 (By similarity).
Synonyms: EPAC 2; cAMP-GEFII; CGEF2; EPAC2; EPAC; Nbla00496
Tractability: Small molecule: a high-quality ligand is known; it belongs to a druggable protein family. Antibody: its Gene Ontology location is reachable by antibodies, with high confidence; UniProt places it where antibodies can reach, with medium confidence. PROTAC: its protein half-life has been measured; a small molecule that binds it is known.
Gene: Protein-coding gene on chromosome 2 (172,735,274 to 173,052,893, forward strand). Ensembl gene ENSG00000091428.
Subcellular location: Cytoplasm; Membrane
Subcellular location (Human Protein Atlas): Focal adhesion sites; Basal body; Cytosol; Mid piece; Plasma membrane
Pathways (Reactome):
Metabolism: Glucagon-like Peptide-1 (GLP1) regulates insulin secretion; Regulation of insulin secretion
Immune System: Rap1 signalling
Signal Transduction: Integrin signaling
Gene Ontology:
Molecular function: guanyl-nucleotide exchange factor activity; protein binding; cAMP binding; small GTPase binding; protein-macromolecule adaptor activity
Biological process: adaptive immune response; G protein-coupled receptor signaling pathway; positive regulation of insulin secretion; Rap protein signal transduction; intracellular signal transduction; regulation of synaptic vesicle cycle; small GTPase-mediated signal transduction
Cellular component: cytosol; membrane; plasma membrane; cytoplasm; hippocampal mossy fiber to CA3 synapse
Genetic constraint (gnomAD): Loss-of-function variants: 52 observed, 120.79 expected, observed/expected ratio (o/e) 0.43, 90% interval 0.34 to 0.54. The upper end of that interval is the gene's LOEUF score, 0.54, which puts it in group 2 of 6, group 1 being the genes least tolerant of losing a copy. Missense variants: 967 observed, 1,187.3 expected, observed/expected ratio (o/e) 0.81, 90% interval 0.77 to 0.86. Synonymous variants: 383 observed, 424.23 expected, observed/expected ratio (o/e) 0.9, 90% interval 0.83 to 0.98.
Homologues: Orthologues: chimpanzee RAPGEF4 (99% identical), macaque RAPGEF4 (99% identical), dog RAPGEF4 (98% identical), rabbit RAPGEF4 (98% identical), mouse Rapgef4 (97% identical), guinea pig RAPGEF4 (96% identical), rat Rapgef4 (95% identical), pig RAPGEF4 (93% identical), tropical clawed frog rapgef4 (87% identical), zebrafish rapgef4a (77% identical), zebrafish rapgef4b (76% identical). Paralogues in human: RAPGEF3 (43% identical), RAPGEF5 (35% identical), RAPGEFL1 (24% identical), RAPGEF2 (20% identical), RAPGEF6 (19% identical), RAPGEF1 (18% identical), RASGRF1 (15% identical), RASGRF2 (14% identical), SOS2 (13% identical), SOS1 (12% identical), RASGEF1B (11% identical), RALGDS (11% identical), and 12 more.
Diseases named in the same sentence as RAPGEF4 in open-access papers:
RAPGEF4 is named in the same sentence as 69 diseases in open-access papers, as found by Europe PMC text mining. Sharing a sentence is not in itself a finding about the gene and the disease. The quoted sentences say what the papers report.
autism (15 papers, 2012 to 2025). Persistent deficits in social interaction and communication and interaction as well as a markedly restricted repertoire of activity and interest as well as repetitive patterns of behavior. "RAPGEF4 (rap guanine nucleotide exchange factor 4) (2q31.1) regulates glutamatergic signaling and is associated with autism." (PMID 40631452, 2025). "More recently, four rare mutations in Epac2/RapGEF4 were identified that associated with autism spectrum phenotypes." (PMID 38463630, 2024). "Moreover, a mutation in the Rapgef4 gene was associated with autism in humans, and the overexpression of this Rapgef4 mutant resulted in an impairment of basal dendrite maintenance in mice." (PMID 29747665, 2018). "RAPGEF4 has been associated with autism and linked to behavioural flexibility in mice." (PMID 26909693, 2016). "Screening of 48 autistic individuals for mutations in the RAPGEF4 gene showed that four rare missense mutations may be a cause of autism." (PMID 27379015, 2016). "Several candidate autism susceptibility genes were hypermethylated (P <0.05) in the HMFA, including Shank3, Cacana1g, Gtf2i, Rapgef4, and Nbea in male offspring and Ext1, Ube3a, Erbb4, Grip1, Grm8, Reeln, Shank3, and Rbfox1 in female offspring." (PMID 24484737, 2014). "Using this method we identified associations with SNPs at the P<10−4 level in or near several genes previously implicated in autism: NLGN4X, RAPGEF4, RORA, FAM135B and CNTNAP2." (PMID 24204716, 2013).
diabetes (9 papers, 2015 to 2026). "Interestingly, at least 12 genes including SLC2A2, G6PC2, SLC30A8, PCSK1 and RAPGEF4, also overlap with previously implicated genes from genome wide association studies (GWAS) for type 2 diabetes mellitus and blood glucose loci." (PMID 31682591, 2020). "Several switch genes, including AKT3, LAMA2, ADCY1, RAB3A, RAPGEF4, and ABCC8, have been implicated in insulin signaling and diabetes." (PMID 36389068, 2022).
Alzheimer disease (4 papers, 2016 to 2023). A progressive, neurodegenerative disease characterized by loss of function and death of nerve cells in several areas of the brain leading to loss of cognitive function such as memory and language. "On the other hand, RAPGEF4 rs17746510 is associated with cognitive decline in Chinese patients with Alzheimer's disease." (PMID 34609028, 2021).
Obesity (3 papers, 2020 to 2023). Accumulation of substantial excess body fat. "The Moo1T strain, which contains Rapgef4, does not have a clear obesity phenotype." (PMID 36717164, 2023).
cognitive decline (2 papers, 2016 to 2021). "Finally, we showed association of several polymorphisms in RAPGEF4 with cognitive decline and mood disturbance in AD patients." (PMID 27598965, 2016).
ovarian carcinoma (2 papers, 2023 to 2025). A malignant neoplasm originating from the surface ovarian epithelium. "Our analysis suggests that the expression of RAPGEF4 in the cAMP signaling pathway is obviously decreased in ovarian cancer cells with stable knockdown of NOP2 expression compared to control cells." (PMID 37800580, 2023). "Lastly, knocking down NOP2 in ovarian cancer reduced the m5C methylation level of RAPGEF4 mRNA." (PMID 41462962, 2025). "The regulatory mechanism of NOP2 on RAPGEF4 in ovarian cancer depends on the m5C methylation level." (PMID 41462962, 2025).
breast carcinoma (1 paper, 2024). "On the other hand, for UNB, specific upregulated DEGs included SMIM3, a leukemia promoter gene, WNT7A, a hypoxia induced EMT driver, PADI2, a tumorigenic breast cancer gene, and RAPGEF4, which modulates gliomas." (PMID 38538643, 2024).
dementia (1 paper, 2016). Loss of intellectual abilities interfering with an individual's social and occupational functions. "We initially demonstrated the significant association of three intronic RAPGEF4 SNPs near the catalytic domain coding sequences with the risk of AD in Chinese patients, suggesting its role in the pathogenesis of AD and development of dementia." (PMID 27598965, 2016). "Interestingly, significant differences in genotype distribution for rs3820841 (intron 17) and rs3769219 (intron 23) in RAPGEF4 were observed among normal control subjects (CDR 0), subjects with very mild dementia (CDR 0.5) and AD patients (CDR 1)." (PMID 27598965, 2016).
mesenchymal tumors (1 paper, 2015). "NOL4 and RAPGEF4 (cluster III) were highly expressed in proneural and weakly expressed in mesenchymal tumors." (PMID 26295306, 2015).
infection (3 papers, 2019 to 2022). The state of being infected such as from the introduction of a foreign agent such as serum, vaccine, antigenic substance or organism. "In addition, genes related to glycerolipid metabolism (Plpp2), glycolysis metabolism (Pfkp), adipocyte differentiation (Rapgef4), nucleotide metabolism (Entpd3), serine catabolism (Shmt1), retinol metabolism (Akr1b10), and lipid-grading metabolism (Pla2g4f) were upregulated after EgPSC infection." (PMID 36713407, 2022).
RAPGEF4 also shares sentences with these, for which no sentence is quoted: Arrhythmia (6 papers); chronic obstructive pulmonary disease (6); Anxiety (5); depression (5); lung carcinoma (5); pancreatic cancer (5); cancer (4); Cardiovascular Disease (3); type 2 diabetes mellitus (3); airway hyperresponsiveness (2); cardiac arrhythmias (2); colitis (2); metabolic disease (2); viral infection (2); Airway obstruction (1); alcohol use disorder (1); alcoholic liver diseases (1); asthma (1); autism spectrum disorder (1); brain edema (1); brain injury (1); chronic asthma (1); cognitive deficits (1); COVID-19 (1); diabetic cardiomyopathy (1); diabetic retinopathy (1); Ebola (1); endolymphatic hydrops (1); enteritis (1); glaucoma (1).
A further 29 diseases each share a sentence with RAPGEF4 in 1 paper.